IL17A (interleukin 17A)
Diseases named in the same sentence as IL17A in open-access papers (continued):
Sharing a sentence is not in itself a finding about the gene and the disease.
pancreatic cancer (90 papers, 2011 to 2026). "The role of interleukin (IL17)A in pancreatic cancer progression is now more defined, and it is known to sustain a pro‐tumoural microenvironment and inhibit the immune response." (PMID 40831074, 2025). "This study supports the use of anti‐IL17A as a strategy for pancreatic cancer and potentially other cancer." (PMID 40831074, 2025). "Subsequent functional experiments provided confirmation of IL‐17A‐mediated regulation of DUOX2 in pancreatic cancer cells." (PMID 38585232, 2024). "All in all, the role of TH17 and IL-17A in pancreatic cancer is not yet fully understood, with evidence suggesting both pro-tumorigenic and anti-tumorigenic effects." (PMID 38835055, 2024). "The study emphasizes the significance of DUOX2 in pancreatic cancer, establishing a connection between its expression, microbial defense, and IL‐17A levels." (PMID 38585232, 2024). "Chandra and colleagues embarked on a study to explore the impact of extra‐tumoral IL‐17A/IL‐17RA signaling on the growth of pancreatic tumors, leading to the observation of unexpected outcomes associated with IL‐17RA deficiency." (PMID 38585232, 2024). "Further research is needed to elucidate the mechanisms through which IL-17A influences pancreatic cancer progression and to determine the potential therapeutic implications of targeting IL-17A in this disease." (PMID 38835055, 2024). "Another study shows that Tc17, a new protumorigenic CD8+T-cell subtype in pancreatic cancer, enhanced tumor development via the IL-17A/RA pathway." (PMID 37686343, 2023). "Studies have shown that pancreatic cancer patients have a distinct tumor microenvironment, and those in stable or remission stages exhibit decreased levels of Treg cells, while IL-17A expression increases." (PMID 37686343, 2023). "Conversely, patients with unresectable advanced pancreatic cancer show the opposite results, with increased levels of Treg cells and decreased IL-17A expression." (PMID 37686343, 2023). "It has a similar effect to IL-17A, promoting the invasion and metastasis of pancreatic cancer and predicting both the prognosis of pancreatic cancer and the efficacy of gemcitabine treatment." (PMID 37686343, 2023). "In several cancers, including colon cancer, lung adenocarcinoma, liver cancer, skin malignant tumors, and pancreatic cancer, IL-17A also affects the therapeutic efficacy and tumor prognosis." (PMID 36119497, 2022). "To investigate the IL-17A/IL-17RA axis in pancreatic cancer, we inhibited IL-17A signaling in a murine model of pancreatic cancer." (PMID 32210079, 2020). "To assess the effect of IL-17A during pancreatic cancer development, we blocked IL-17A signaling with monoclonal antibodies in a murine pancreatic cancer model." (PMID 32210079, 2020). "We retrieved IL-17RA and IL17A gene expression levels from publicly available transcriptomic data of 903 patients with pancreatic cancer." (PMID 32210079, 2020). "IL-17A expression was reported to elevate in Treg-decreased patients with unresectable pancreatic cancer after chemotherapy, suggesting its role in immune escape." (PMID 31159823, 2019). "Indeed, in Pancreatic cancer, IL17A blockade enhances the recruitment and activation of CD8 T cells and NK cells, an effect amplified when combined with a cancer vaccine." (PMID 40831074, 2025). "IL-17A and IL-17B were two subtypes closely related to pancreatic cancer in the IL-17 family." (PMID 41384105, 2025). "This approach paves the way for novel therapeutic combinations in pancreatic cancer, where IL17A depletion may boost both immunotherapy efficacy and anti‐tumour responses." (PMID 40831074, 2025). "Overall, this study provides new insights into the effects of IL17A in modulating the intensity of both antigen‐specific humoral and cellular responses and the anti‐tumour response induced by a DNA anti‐cancer vaccine in pancreatic cancer." (PMID 40831074, 2025).
pancreatic cancer (continued). "We used genetically engineered mice proficient or deficient in IL17A, and orthotopically injected mice with pancreatic tumour cells depleted or not in IL17A, to examine the vaccine effects on tumour growth and immune responses." (PMID 40831074, 2025). "The pivotal finding of the study elucidated that extra‐tumoral IL‐17RA deficiency or blockade unexpectedly elicited the secretion of IL‐17A in response to microbial stimuli, subsequently leading to the systemic elevation of IL‐17A levels and promoting the growth of pancreatic tumors." (PMID 38585232, 2024). "Some evidence has demonstrated that combining anti-IL-17A antibodies with gemcitabine represents an effective approach to enhancing the antitumor response by modulating macrophages, particularly in pancreatic cancer, for which gemcitabine is currently the most widely used anticancer drug." (PMID 37686343, 2023). "However, we found no increased cell motility and sphere formation when treating pancreatic cancer cells with recombinant IL-17A." (PMID 32210079, 2020). "It is unclear whether this observation is also valid for pancreatic cancer, and whether IL-17A/IL-17RA neutralization is a promising therapy for PDAC." (PMID 32210079, 2020). "Here, we ask whether IL-17A promotes the aggressiveness of pancreatic cancer both in vitro and in vivo." (PMID 32210079, 2020). "Furthermore, peritumoral injection of recombinant IFNγ or IL-17A inhibited colon and pancreas tumor growth compared to controls." (PMID 33042110, 2020). "IL-17A has been shown to induce stem cell features in pancreatic cancer precursor PanIN cells." (PMID 32210079, 2020). "If this mechanism functions in invasive pancreatic cancer, blocking IL-17A could be a promising therapy to target the altered immune response." (PMID 32210079, 2020). "As IL-17A accelerates PanIN progression and PanIN is a precursor lesion of pancreatic cancer, we hypothesized that IL-17A might drive pancreatic cancer initiation and early progression." (PMID 32210079, 2020). "Splenic proteins associated with muscle and body weight preservation in the pancreatic cancer PDX mice (IFNγ, IL-17A) were produced at higher levels in the less cachectic PDX group and splenic IL-8, associated with body weight loss, was produced at higher levels in the more cachectic PDX group." (PMID 30513792, 2018). "In addition, manipulation of IL-17A by overexpression of IL-17A in the pancreas or knockout of IL-17A in hematopoietic cells interfered initiation and development of pancreatic tumor in vivo." (PMID 29379802, 2017). "Furthermore, L-4F led to down-regulation of IL-17A and IL-4, suggesting that, in addition to its direct anti-inflammatory effect, L-4F can change the phenotypes of TAMs in pancreatic tumors by altering the microenvironment." (PMID 29245934, 2017). "Recent studies have proposed that IL-17A could act as a potential treatment option for pancreatic cancer by crossing a mouse model of idiopathic PDAC (KPC) with IL-17A knockout mice and that cells with intact IL-17A and IL-17A-deficient cells had very different characteristics." (PMID 37686343, 2023). "IL-17A increases PD-L1 expression through the p65/NRF1/miR-15b-5p axis and promotes resistance to anti-PD-1 therapy, and IL-17F might be associated with a favorable overall survival in pancreatic cancer patients who were treated with gemcitabine." (PMID 37686343, 2023). "IL-17A and IL-17B are primarily involved in the regulation of the tumor immune microenvironment, and they particularly play a special role in the drug resistance and inflammatory response in pancreatic cancer, according to our overview of six different cytokines." (PMID 37686343, 2023). "The function of IL-17 may also vary depending on the disease phase, and in pancreatic cancer it has been proposed that IL-17-producing cells support tumor growth in the initial phases of the disease, while in advanced phases, IL-17A potentiates antitumor immunity." (PMID 33244315, 2020).
pancreatic cancer (continued). "We have asked whether the IL-17A/IL-17RA axis promotes the aggressiveness of pancreatic cancer." (PMID 32210079, 2020). "Our current in vitro and in vivo data could not show an association between IL-17A/IL-17RA signaling and the aggressiveness of pancreatic cancer." (PMID 32210079, 2020). "Recent research has revealed the existence of a non-canonical CD8+ T-cell subpopulation that produces IL-17A, which can promote pancreatic cancer progression through IL-17RA signaling." (PMID 37686343, 2023). "Blocking the IL-17A/IL-17RA axis in a murine pancreatic cancer model did not improve the survival of mice, but reduced the tumor burden slightly." (PMID 32210079, 2020). "While we have shown IL-17RA expression in both human and murine pancreatic cancer cells, IL-17A does not increase “aggressiveness” of pancreatic cancer cell lines in terms of inducing cancer stem cell features." (PMID 32210079, 2020). "Together, these results suggest that IL-17A/IL-17RA expression does not affect the survival of pancreatic cancer patients." (PMID 32210079, 2020). "Blocking the IL-17A/RA axis via antibodies alone is not able to effectively stop pancreatic cancer development and progression." (PMID 32210079, 2020). "In contrast to PanIN cells, stem cell features in pancreatic cancer cells seems to be independent of IL-17A." (PMID 32210079, 2020). "CD44 expression was not different in IL-17A treated Panc02 murine pancreatic cancer cells compared to the controls (1.73% vs. 1.38%)." (PMID 32210079, 2020). "The addition of IL-17A to pancreatic cancer cells did not increase the subpopulation of cells expressing the typical stem cell markers such as CXCR4, ABCG2, and CD44." (PMID 32210079, 2020). "To assess the efficiency of IL17A depletion in enhancing the immune responses elicited by the ENO1‐DNA vaccine, with a particular focus on the cytotoxic response that had previously remained undetected, we employed both autochthonous and transplantable orthotopic mouse models of pancreatic cancer." (PMID 40831074, 2025). "Compared to healthy individuals, pancreatic cancer patients have remarkably higher serum levels of IL-17, and PDAC development and metastasis may be impacted by increasing levels of circulating Th17 cells and serum IL-17A." (PMID 37686343, 2023). "Blocking IL-17A/IL-17RA signaling does not interfere with pancreatic cancer development and progression and may not be considered as a promising monotherapy for PDAC." (PMID 32210079, 2020). "Treatment of pancreatic cancer cell lines MIA PaCa-2 and Panc02 with human respective mouse recombinant IL-17A protein (20 ng/mL) did not change cell motility in the wound healing assay after 24 and 48 h." (PMID 32210079, 2020).
periodontal disease (90 papers, 2011 to 2026). "IL-17A cytokine in periodontal diseases was significant associated with disease progression and severity of destruction." (PMID 34514065, 2021). "Although the expression of proinflammatory cytokines associated with periodontal disease pathogenesis (such as, IL-1β, IL-6, IL-17A, and TNF) was inhibited, statistical significance was reached only for IL-17A, which was downregulated by 4.9-fold." (PMID 31581596, 2019). "Thus, we chose this practical index for the representation of periodontal status and still found that the levels of IL-17A were strongly associated with periodontal disease severity." (PMID 32053656, 2020). "Increased IL-17A expression was observed in patients with a history of aggressive periodontal disease; an increase of IL-17A from day 10 to 4 weeks was also observed in this group but not in periodontally healthy controls." (PMID 39685706, 2024). "The cytokines most implicated in periodontal disease include TNF-α, IL-1β, IL-6, IL-17A, INF-γ, IL-8, and, to a lesser extent, IL-12 and IL-18." (PMID 39062000, 2024). "These indicated that IL-17A cytokines play a role in potentially promoting inflammatory and periodontal disease." (PMID 34514065, 2021). "In human studies, IL-17A-producing cells were more abundant in the gingival tissue of patients with periodontal disease than in healthy gingival tissue, resulting in infiltration of IL-17A-producing cells and inflammation of periodontal disease tissue." (PMID 33918456, 2021). "Elevated levels of IL-17A have been measured in periodontal diseases characterized by high grade chronic inflammation." (PMID 32560286, 2020). "Neutrophil deficiency, arising from antibody-mediated depletion or defective recruitment, results in susceptibility to IL-17A-associated infections, such as OPC and periodontal disease." (PMID 26213975, 2015). "This could be attributed to the involvement of IL-17A in the progression of periodontal disease remaining unclear." (PMID 37623290, 2023). "A shift toward production of pro-inflammatory cytokines such as IFN-γ and IL-17A could have significant implications for pathogenesis of periodontal disease." (PMID 32391008, 2020). "IL-17A and IL-17F have a very similar amino acid sequence and both play similar functions and have the ability to induce chemokines which is crucial to the neutrophil recruitment and activation, the first wall in the periodontal diseases." (PMID 26339129, 2015). "It is, therefore, suggested that IL-17A might be an interesting target for development of new therapies for periodontal disease, an assertion that needs testing in further cohorts and clinical trials." (PMID 23304063, 2012). "Patients with a high BOP ratio have been found to have higher IL-17A concentrations in the saliva and gingival crevicular fluid compared with those without periodontal disease." (PMID 33050355, 2020). "As a treatment for suppressing the Th17 axis, IL-17A and IL-23 inhibitors have been clinically applied as therapeutic agents for inflammatory bowel disease and psoriasis, and these drugs may be effective against NAFLD and periodontal disease." (PMID 33918456, 2021). "In support, inflammatory cytokines IL-6, IL-17A, and IL-33 were increased in the saliva of SLE/periodontal disease patients compared to non-SLE subjects with periodontal disease." (PMID 34950607, 2021).
Anxiety (89 papers, 2014 to 2026). Intense feelings of nervousness, tension, or panic often arise in response to interpersonal stresses. "Preclinical research on mice indicates that IL-17A significantly contributes to the development of anxiety associated with epilepsy, stroke, or chronic stress." (PMID 38956309, 2024). "Meanwhile, IL-17A change from baseline to D7 was negatively associated to anxiety (P=0.001) and cognitive impairment (P=0.017) at discharge." (PMID 37878890, 2023). "These inflammatory markers were related to serum and hippocampal IL-17A and associated with anxiety-like behavior." (PMID 35216112, 2022). "To confirm the anti-anxiety effect of IL-17A deficiency in chronic epilepsy, we employed another widely used behavioral assay for testing anxiety status, the EPM test." (PMID 35875667, 2022). "Multiple studies have linked TNFα with anxiety-like behavior in other animal models and human studies, but less is known about serum IL-17A and anxiety-like behavior." (PMID 35216112, 2022). "Taken together, our data demonstrated that IL-17A deletion mitigates TLE-associated anxiety behavior, possibly via the hippocampal neuroprotection and the reduction of seizure-induced aberrant neurogenesis." (PMID 35875667, 2022). "While this could be a direct relationship to anxiety, IFNγ was also related to serum TNFα and IL-17A, the latter of which was also significantly associated with both hippocampal IL-17A and to anxiety-like behavior." (PMID 35216112, 2022). "Thus, in the present study, we investigated the role of IL-17A in epilepsy-associated anxiety and its biological mechanisms, using IL-17A wildtype (WT) and IL-17A knockout (KO) mice subjected to pilocarpine-induced status epilepticus (SE)." (PMID 35875667, 2022). "Since adult neurogenesis is involved in the regulation of anxiety, we next evaluated whether IL-17A deficiency could modulate seizure-induced hippocampal neurogenesis." (PMID 35875667, 2022). "fosB KO mice showed an increased number of hilar ectopic cells after kainic acid (KA)-induced acute seizures, and manifested increased anxiety, in agreement with our IL-17A data demonstrating that reduced EGC production in IL-17A KO could attenuate epilepsy-associated anxiety." (PMID 35875667, 2022). "Gut microbial signals activate meningeal γδ T cells to produce IL-17A, resulting in IL-17A receptor signaling on neurons and subsequent abnormal anxiety-like behaviors." (PMID 40804450, 2025). "For example, meningeal γδ T cells, which secrete high levels of IL-17A, play a crucial role in modulating anxiety-like behaviors by signaling to neurons with IL-17RA within the medial prefrontal cortex (mPFC)." (PMID 40804450, 2025). "This study also revealed that female PD patients exhibited significantly higher plasma IL-17A levels than male patients, with IL-17A levels positively correlating with anxiety but inversely with cognitive deficits." (PMID 40469524, 2025). "Accordingly, in mice, IL-17A and IL-17C can activate basolateral amygdala neurons with IL-17 receptor A, promoting anxiety-like behaviors, whereas IL-10 opposes this pathway." (PMID 40804450, 2025). "In summary, neutralizing IL-17a alleviated the anxiety of ASD model mice and improved social deficits." (PMID 38993386, 2024). "The discovered connection between increased levels of IL-17A and IL-23A and the intensity of anxiety in patients with GAD provides opportunities for therapeutic intervention." (PMID 38956309, 2024). "Il-17a-/- mice or injection of anti-IL-17a neutralizing antibodies into the cisterna magna in WT mice showed a significant decrease in anxiety-like behavior." (PMID 37608988, 2023). "For example, pharmacological blockade of CXCR4 attenuates the conditioned rewarding and locomotor stimulant effects of MDPV, while blockade of CXCR4, CCR5, or IL-17A signaling attenuates changes in anxiety-like behaviors evoked by MDPV." (PMID 38025384, 2023).